INS (insulin)
Diseases named in the same sentence as INS in open-access papers (continued):
Sharing a sentence is not in itself a finding about the gene and the disease.
diabetes (continued). "Using binary logistic regression, a high level of non-HDL cholesterol and insulin therapy were found to be associated with the risk of developing scleroedema in patients with diabetes mellitus; however, it should be mentioned that the associations with HSI and BMI were nearly significant." (PMID 33952255, 2021). "Likewise, in older adults without diabetes, the association of the insulin sensitivity index or fasting insulin concentration with all-cause mortality disappeared after adjustment for eGFR." (PMID 33715620, 2021). "Therefore, excessive ER stress or attenuation of the UPR in IPCs could cause functional inhibition of the cell functions, resulting in reduced secretion of insulin, eventually leading to onset of diabetes." (PMID 34769468, 2021). "Diabetes mellitus (DM) is a metabolic disease characterized by chronic hyperglycemia as a consequence of defects in insulin action, secretion, or both." (PMID 34062938, 2021). "While a function of insulin is translocating K into cells, in diabetes mellitus (DM) patients, such translocation tends to be inhibited due to decreased endogenous insulin secretion." (PMID 34063969, 2021). "Additionally, there is a need to investigate glucose-lowering polymer synergetic effects, such as cellulose, which positively impacts diabetes mellitus type 2, and inulin, which was reported to reduced serum insulin levels but simultaneously increased body weight in diabetic rats." (PMID 33806527, 2021). "Although the prevalence of insulin monotherapy among patients with type 2 diabetes in Bangladesh accounts for less than 7.3% to 14.0%, additional research is needed to provide evidence-based guidelines for long-term diabetes patients in Bangladesh to keep control of the periodontal disease." (PMID 33822810, 2021). "When the patients were asked about whether they were willing to start insulin therapy if their physician advised it as the only treatment to control diabetes, 99 (48.8%) patients stated that they would initiate therapy, while 104 (51.2%) patients were found to be unwilling." (PMID 34712538, 2021). "Additionally, whilst systemic hyperglycaemia is a fundamental feature of DCM (and diabetes in general), evidence from rodent models of diabetes indicates that cardiac specific insulin resistance is one of the earliest detectable pathological events, prior to the deterioration of cardiac function." (PMID 34113491, 2021). "However, similar studies in a rat model of insulin-deficient diabetes showed no meaningful increase in retinal glycolysis." (PMID 34861815, 2021). "A meta-analysis of 11 randomized controlled trials found a significant influence of RES as a treatment for diabetic parameters such as fasting glucose, insulin, glycated hemoglobin, and insulin resistance in patients with diabetes mellitus (DM) type II." (PMID 34578972, 2021). "Of note, it was also recently commented that persons with and without T2D can have a similar beta-cell mass, but because of huge variabilities in insulin sensitivity and insulin secretion in the general population, the total mass is inadequate and might be responsible for their diabetes." (PMID 34069914, 2021). "Participants had an average of 2.4 (1.2) diabetes complications and 2.5 (1.7) co‐morbidities; and 9.2 (9.0) different prescriptions and 1.5 (1.0) different GLTs in the 6 months before study entry; also, 3803 participants (20.0%) had insulin prescriptions during that time." (PMID 33565708, 2021). "While AID and manual insulin delivery systems have reached their peak in terms of performance, the inclusion of clinically relevant analytes and detection techniques could markedly improve diabetes management, as well as reduce T1D‐related complications." (PMID 34027090, 2021). "Diabetes mellitus (DM) is a chronic disease that occurs due to insufficient insulin production or ineffective insulin utilization by our body." (PMID 34424924, 2021).
diabetes (continued). "Diabetes mellitus (DM) is a group of metabolic disorders characterized by chronic hyperglycemia due to defects in insulin secretion, action, or both which leads to metabolic disturbances." (PMID 34167465, 2021). "Without combination with an immune protection approach, such as immunosuppressants or encapsulation devices, SC‐islets could not treat diabetes caused by autoimmune destruction of the insulin‐producing cells, such as in T1D." (PMID 34155834, 2021). "As a matter of course, there are many more technologies that have proven to be effective in diabetes management in general, for example, continuous glucose monitoring systems, continuous subcutaneous insulin infusions, and sensor augmented insulin pumps or closed-loop systems." (PMID 33908894, 2021). "In this particular review, we aimed to compare PIs towards their effects on insulin sensitivity and the onset of diabetes mellitus (DM) in patients with HIV." (PMID 34790115, 2021). "Further research is needed in order to determine whether these properties are generalizable to retinal tissue, but it is possible that the decrease in IL-15 signaling reflects the impaired glucose and insulin responses that ultimately precipitate diabetes complications such as retinopathy." (PMID 34861815, 2021). "This may imply that the contribution of adequate Mg supply to glucose uptake is not only dependent on the modulation of insulin action as has been proposed in human patients with diabetes mellitus, but may also include insulin-independent targets, especially in ruminants." (PMID 34072724, 2021). "Diabetes mellitus (DM) is a group of metabolic disorders characterized by hyperglycemia resulting from defects in insulin secretion, insulin action, or both." (PMID 35004072, 2021). "In summary, the reviewed evidence suggests that a carbohydrate-last meal pattern might have potential in improving PP glucose response in patients with T1D and T2D, therefore macronutrient order should be considered to inform insulin dosing and diabetes management." (PMID 33918343, 2021). "Hence, the absence of insulin or the cell is not sensitive to consume insulin leads to raise blood sugar level, which is the hallmark of diabetes." (PMID 33494764, 2021). "In this context of old patients with long standing diabetes, the utility of therapeutically targeting glycemia, particularly through insulin sensitization, is questionable as it may result in exposure of cells and tissues to additional nutrients that will further challenge their survival." (PMID 33608002, 2021). "Although restoration of serum insulin to the levels near normal values might be one of factors to compensate deleterious effects of diabetes, however the resone for high levels of FGF21 relation to phenolics and flavonoids as well as glibenclamid needs furder examination." (PMID 34233693, 2021). "Some studies have reported a successful regression of pre-existent diabetes in up to two thirds of cases, whereas other authors have found a substantial lack of improvement at one-year follow-ups, as shown by a markedly low insulin response during the oral glucose tolerance test (OGTT)." (PMID 33800465, 2021). "According to the diabetes guidelines, all patients with diabetes should participate in self-management education and behavior modification such as nutritional therapy, physical activity, appropriate use of medication and insulin, prevention and treatment of hypoglycemia, and psychological wellness." (PMID 34065775, 2021). "As severe CFTR genotype increases the risk of diabetes independently of pancreatic exocrine dysfunction, a screening for prediabetes is mandatory in patients with two severe CFTR mutations, particularly F508del, and insulin supplementation seems a rational therapy to consider." (PMID 33810109, 2021). "Diabetes mellitus (DM) is a complex metabolic disorder characterized by chronic hyperglycemia due to inadequate insulin secretion and/or insulin resistance." (PMID 34830295, 2021).
diabetes (continued). "Also, among patients with and without CKD, the risk for recurrent CVD events is higher among those with diabetes taking versus not taking insulin." (PMID 33648518, 2021). "Diabetes mellitus (DM) is a syndrome characterized by decreased insulin secretion and/or tissue insulin sensitivity and altered metabolism of carbohydrates, lipids and proteins, in addition to increased cardiovascular risks." (PMID 33277985, 2021). "The next logical step in the evaluation of these and possibly other maximal models of the glucose-insulin system would be to compare their predictions against actual observational data, obtained with different experimental set-ups in patients with a range of normal and diabetes conditions." (PMID 34570804, 2021). "Additionally, IGF improves insulin signaling, which could explain the beneficial effects obtained with TT extracts in diabetes, but the exact mechanism of action is not fully known." (PMID 32408715, 2020). "Lastly, the data of some other elements such as diet and insulin levels, which may confound the association between Cre/BW and diabetes, were lacking." (PMID 31952309, 2020). "Diabetes mellitus (DM) is a group of metabolic diseases characterized by hyperglycemia as a result of defects in the secretion or action of insulin or both." (PMID 32831908, 2020). "However, if animals with 3‐months of diabetes were treated with one month of insulin then the levels of glucose in detrusor, as well as the majority of metabolites and metabolic pathways, were normalized and not significantly different to non‐diabetic, age‐match controls." (PMID 33200530, 2020). "Diabetes mellitus (DM) is a highly prevalent heterogeneous group of metabolic disorders characterized by hyperglycemia due to an absolute or relative deficit in insulin production or action." (PMID 33732147, 2020). "Physician related factors with respect to insulin therapy can contribute to diabetes mellitus (DM) mismanagement." (PMID 32957991, 2020). "In the present study, we tested the hypothesis that non-invasive spectral biomarkers can be identified in saliva of hyperglycemic diabetic and in insulin-treated diabetic rats, and the differentially expressed vibrational modes can be employed as salivary biomarkers for diabetes monitoring." (PMID 32182246, 2020). "Diabetes mellitus (DM) comprises a group of metabolic diseases characterized by hyperglycemia resulting from defects in insulin secretion, insulin action, or both." (PMID 32952944, 2020). "In addition, as this was a volunteer sample, these participants may be more motivated toward successful self-management of their diabetes and transition to insulin." (PMID 32406854, 2020). "Serotonin plays a key role in controlling insulin secretion and its absence could lead to diabetes." (PMID 33381523, 2020). "However, some persons with diabetes identified practical concerns such as an inability to carry medications (especially insulin) when travelling which might lead to missed dosages." (PMID 33091039, 2020). "Previous duration of diabetes was negatively correlated with the percentage of “time-within-remission range”, OR 0.89, (0.86–0.92), p < 0.0001, as was baseline HbA1c, OR 0.85, (0.74–0.97), p = 0.0184 and treatment with insulin, OR 0.24, (0.17–0.35), p < 0.0001." (PMID 32283783, 2020). "However, insulin is only able to promote lipogenesis but not to block gluconeogenesis in the insulin-resistant liver, exacerbating liver steatosis associated with diabetes." (PMID 33679386, 2020). "Our goal was to determine the association of insulin resistance indexes with cardiac autonomic function – measured by 48-h ambulatory electrocardiogram monitoring – in a population of older adults without diabetes." (PMID 32393179, 2020). "Diabetes mellitus (DM) is the most abundant chronic and metabolic illness characterized by an elevation in blood glucose levels because of the absolute or relative insulin deficit." (PMID 32977706, 2020).
diabetes (continued). "However, patients diagnosed with diabetes on insulin or oral hypoglycemic agents may suffer severe hypoglycemia if their medication regimen is not properly managed during the initiation of KD." (PMID 32923239, 2020). "Diabetes mellitus (DM) is a metabolic disease characterized by hyperglycemia resulting from abnormal insulin secretion and/or action." (PMID 33841541, 2020). "Diabetes mellitus is an endocrine disorder with heterogeneous etiologies, which is characterized by raised levels of glucose in a person's blood and disturbances of macromolecules such as carbohydrate, fat, and protein metabolism resulting from defects in insulin secretion, insulin action, or both." (PMID 32766315, 2020). "Metformin is the first-line drug for glycemic control, as it effectively reduces hepatic glucose production and improves insulin sensitivity in Type 2 diabetes mellitus in the clinic for more than five decades without stimulating insulin secretion, additional weight gain, or causing hypoglycemia." (PMID 32010479, 2020). "Diabetes mellitus (DM) is a devastating metabolic disease in which insulin secreting β-cells in the islets of Langerhans are damaged to different extent." (PMID 32064260, 2020). "Furthermore, the fetus of a diabetic mother would have developed pancreatic hyperplasia by the time the diagnosis of diabetes is made between 24 to 28 weeks or even later, and already has inappropriate insulin secretion that persists along with pregnancy, despite treatment and good glycemic control." (PMID 33182482, 2020). "The impairment of insulin signalling, the presence of chronic inflammation and hyperglycaemia, the accumulation of advanced glycation end-products (AGEs) and increases in oxidative stress play an essential role in the pathogenesis of both diabetes and Alzheimer’s disease." (PMID 32005901, 2020). "Consequently, DGC acts as a cellular signaling node containing plakoglobin as a pivotal subunit, and perturbation of plakoglobin function (e.g., by Trim3221) probably contributes to the insulin resistance seen in various catabolic states (e.g., untreated diabetes, obesity)." (PMID 32170063, 2020). "Diabetes mellitus (DM) is a serious and chronic disease resulted from the pancreatic beta-cells’ insulin secretion disorder." (PMID 32879331, 2020). "Diabetes may influence the neoplastic process by several mechanisms, including hyperinsulinemia (either endogenous due to insulin resistance or exogenous due to administered insulin or insulin secretagogues), hyperglycemia, or chronic inflammation." (PMID 32873885, 2020). "Although diabetes or prediabetes risk persists during ART, our observation that it is only apparent by HbA1c suggests that during ART, hepatic insulin resistance may be a driver of hyperglycemia, possibly due to liver fat accumulation or other adverse effects of ART drugs." (PMID 32267855, 2020). "Diabetes mellitus (DM) is a group of metabolic diseases characterized by hyperglycemia as a result of insulin secretion/action defects." (PMID 33371208, 2020). "This may explain the lack of association of pancreatic steatosis with insulin secretion and diabetes reported in some clinical studies." (PMID 32725157, 2020). "Diabetes mellitus (DM) is a systemic metabolic disease wherein patients suffer from persistently elevated blood glucose levels as a result of impaired insulin production or sensitivity as a result of different environmental and genetic factors." (PMID 33290260, 2020). "Insulin has been described to have a permissive role in facilitating the action of GH, and relatively low levels of IGF may increase the risk of weight gain in diabetes patients." (PMID 33905470, 2020). "The usual cause of diabetes is lack of effective insulin in the body." (PMID 32952842, 2020).
diabetes (continued). "The direct binding of SARS-CoV-2 to ACE2 on β-cells might contribute to β-cell damage and insulin deficiency, which, combined with cytokine-induced insulin resistance and hypokalemia-related inhibition of insulin secretion, contributes to worsening glucose control in patients with diabetes mellitus." (PMID 33297431, 2020). "Thus, compounds that improve mitochondrial function which further augment insulin signaling pathway in skeletal muscle could be a potential therapy in the treatment of diabetes mellitus." (PMID 32987623, 2020). "Therefore, we recommend that the Ministry of Health of Saudi Arabia takes appropriate steps to increase the number of qualified physicians to deal with patients on insulin pump therapy, particularly considering the constantly increasing number of diabetes cases in Saudi Arabia every year." (PMID 33334003, 2020). "In addition, the ABCA1 R230C polymorphism may play an important role in maintaining glucose-mediated insulin secretion, in turn, leads to a 4-fold increase occurrence of diabetes." (PMID 32600448, 2020). "Similarly, a Diabetes UK Position Statement advocates that hyperglycemia following steroid administration be managed by variable rate intravenous- or continuous subcutaneous insulin infusion." (PMID 33519707, 2020). "Similarly, “Ghritkumari” (aloe vera) is used as a remedy for both constipation, due to its laxative property which relieves constipation by promoting intestinal motility, as well as diabetes, as aloe vera is believed to improve insulin secretion and enhance pancreatic β cell function." (PMID 32537731, 2020). "Interestingly, a honeymoon period has been described in an estimated 50% of new onset pediatric patients where their symptoms seem to improve and they experience clinical remission of diabetes upon the first administration of insulin and the subsequent reduction in dosage." (PMID 33339173, 2020). "Using continuous glucose monitoring on patients with diabetes, Kazempour-Ardebili et al15 showed lower mean glucose levels by −36 to −190 mg/dL during dialysis days compared with days off dialysis; and Sobngwi et al16 showed that total daily insulin needs can decrease by ~25% on hemodialysis days." (PMID 32111715, 2020). "However, in the subgroup analysis with patients whose duration of diabetes mellitus was relatively short (less than 5 years), fasting insulin significantly decreased from 11.1 to 6.3 mcIU/ml and HOMA-IR significantly improved from 3.39 to 2.08 (p = 0.044 and p = 0.046, respectively)." (PMID 32025522, 2020). "Diabetes mellitus (DM) is defined as a ‘‘group of metabolic diseases characterized by hyperglycemia resulting from disturbances in insulin secretion, action or both’’." (PMID 33322243, 2020). "Type 2 Diabetes Mellitus (T2DM) is one of the most common metabolic disorders worldwide and its development is primarily caused by a combination of two main factors: defective insulin secretion by pancreatic β-cells and the inability of insulin-sensitive tissues to respond to insulin." (PMID 32872570, 2020). "Moreover, our study showed that inhibition of mmu_circ_0000529 overexpression in adipose tissues of obese mice could increase insulin sensitivity and glucose tolerance, implicating circSAMD4A in the pathogenesis of diabetes." (PMID 32292524, 2020). "Subsequent risk-adjusted analysis revealed that insulin use in patients without diabetes was again associated with an increased combined incidence of complications and mortality when compared with those not receiving insulin (OR=1.54; 95% CI 1.15-2.04; P=0.003)." (PMID 33118731, 2020). "The design of these novel materials based on metal ions could be an excellent tool to improve the distribution and, therefore, the effectiveness of metals as oral anti-diabetic agents in the treatment of diabetes mellitus, giving an alternative to traditional insulin therapy." (PMID 32365648, 2020).